FOXP3 (forkhead box P3)
Diseases named in the same sentence as FOXP3 in open-access papers (continued):
Sharing a sentence is not in itself a finding about the gene and the disease.
cancer (continued). "We performed clustering based on the CD8/FOXP3 ratio, PD-1 and PD-L1 immune checkpoint expression and stratified patients into 3 clusters with different prognostic markers to guide cancer immunotherapy (anti-PD-1/PD-L1 therapy or targeting of Treg cells)." (PMID 35222387, 2022). "FOXP3 was mainly expressed in Tregs and plays a role in promoting cancer, suggesting that the infiltration of FOXP3-positive Tregs promotes the occurrence and development of NSCLC and provides a new target for its immunotherapy." (PMID 36550816, 2022). "A growing number of FoxP3+ Treg cells brought about bile duct invasiveness, balanced cancer microenvironment homeostasis, and a high chance of relapse in intrahepatic CCA." (PMID 36301031, 2022). "What was interesting was the finding that FoxP3 expression also increased the probability of survival in cancers such as head and neck squamous cell carcinoma and stomach adenocarcinoma." (PMID 35326588, 2022). "TILs included CD4+, CD8+, and FOXP3+ T cells, and all subsets were significantly reduced in the cancerous tissues compared to the cancer stromal tissues." (PMID 36458816, 2022). "In the BJCYH cohort, IHC assays demonstrated that the levels of CD8+ T cells were decreased while FOXP3+ T cells were increased in cancer tissues in comparing with matched normal tissues." (PMID 36458816, 2022). "Both were expressed in the vicinity of the cancer cells and the stromal region, though FOXP3 positive cells were observed in very small numbers when compared to CD206 positive cells." (PMID 35773436, 2022). "FOXP3+ Treg cells can intervene in cancer angiogenesis in two ways: through the VEGF pathways or the modulation of other immune cells with inflammatory cytokine release." (PMID 36569832, 2022). "It is well known, that the Treg marker FoxP3 can be upregulated or downregulated depending on the human cancer type." (PMID 36098901, 2022). "FoxP3+ regulatory T cells are essential guardians of immune homeostasis but also limit efficient immune responses to malignancies." (PMID 34423375, 2022). "In some cancers, overexpression of FOXP3 significantly induces cell proliferation, migration, and invasion, and its inhibition will impair its carcinogenic function." (PMID 35309319, 2022). "CD4+CD25+FOXP3+Treg cells play a key role in the aggressiveness of diseases and cancers by regulating the immune response." (PMID 35664563, 2022). "Normal epithelium of non‐cancer patients displayed also FoxP3+ cells in 88.9% of the specimens, PD‐L1+ cells in 44.4% of specimens, and no M1 and M2 macrophage phenotypes in any of the specimens." (PMID 34626165, 2022). "We have therefore primarily studied levels of Foxp3 (+) cells in malignant tumors from 170 patients related to prognosis of the patients." (PMID 35326661, 2022). "The infiltration of tumors with FOXP3+ Tregs was considered unfavorable for patient survival in many types of cancer." (PMID 35719936, 2022). "Another strategy currently followed to selectively deplete Tregs in cancer are antisense oligonucleotide against FOXP3." (PMID 36405718, 2022). "Consistently, we observed that the frequency of protumorigenic subtypes, Th2 and FOXP3+ Treg cells significantly increased in the draining lymph nodes of patients with different cancers including BC." (PMID 36038861, 2022). "PD-L1 expression has been shown to correlate with Cancer-Forkhead box P3, which can promote immune evasion in PDAC by recruiting Forkhead box P3+ Treg cells via CCL5 upregulation." (PMID 35626033, 2022). "CD4+ T cells that express the FOXP3 transcription factor function as Treg cells that suppress effective immune responses against cancer cells." (PMID 36253752, 2022). "Fork head box protein 3 (FoxP3)+ regulatory T cells (Treg) are important immune regulatory cells, which play an important role in the development of many kinds of malignant tumors." (PMID 35783156, 2022).
cancer (continued). "Metastatic tumors with matched pre- and post-HIPEC samples (nine patients) were stained with CD3, CD8, FOXP3, PD-1, and pan CK; pan CK represents cancer island staining." (PMID 35357903, 2022). "Fork head box p3 (FOXP3), the specific transcription factors of Tregs, not only in Tregs, but also expressed in cancer cells of certain malignant tumors." (PMID 36550816, 2022). "The correlations of CD8+ and GrB+ lymphocytes with immunosuppressive factors (PD-L1, IDO, FoxP3 Tregs and TAMs) were evaluated from malignant tumors." (PMID 36551965, 2022). "Other approaches in targeting Tregs for cancer interventions include activation of epigenetic regulatory complexes that function to repress Foxp3 and Treg function." (PMID 35795673, 2022). "(E) The numbers of CD4+, CD8+, and FOXP3+ T cells in cancer tissues of BJCYH cohort were compared between VPS9D1-AS1 negative and positive tissues." (PMID 36458816, 2022). "Expression of FoxP3 was highly and positively correlated with the expression of Helios on T cells within PBMCs and TILs in cancer patients." (PMID 35655158, 2022). "The results suggest that the synergic activity of vaccination and FoxP3-inhibitor ASO can be a novel strategy for cancer treatment." (PMID 36012138, 2022). "Celastrol reportedly directly suppresses T-cell proliferation and Th17 cell induction, while facilitating forkhead box P3 (Foxp3) expression and Treg cell proliferation, indicating an immune suppression phenotype in cancer." (PMID 36120370, 2022). "The American cancer society suggests a 5-year overall survival of 81% for EC patients, which is surpassed by the FoxP3 low group and clearly missed by the FoxP3 high group." (PMID 36098901, 2022). "The data reported here revealed a strong correlation between CD4, CD25 and FoxP3 markers, indicating a high incidence of Treg cells, which in turn correlated with dysplastic progression to carcinoma." (PMID 36009387, 2022). "The Foxp3+ICOS+/Foxp3+ cell ratio in carcinoma and peritumor tissue were higher than that in normal tissue." (PMID 35311157, 2022). "Instead, the ontogeny of Tregs in human cancer samples can be assessed ex vivo either via TCR repertoire sequencing or via epigenetic analysis of the CNS2 element in the FOXP3 gene, which is demethylated in tTregs but mostly methylated in pTregs." (PMID 34632244, 2021). "In Treg cells, Mef2d is required to sustain and integrate the Foxp3 transcriptional repertoire; Mef2d deletion in Foxp3+ cells impairs the acquisition of an eTreg phenotype and leads to an increase in anti-cancer immunity and transplant rejection." (PMID 34290714, 2021). "The increased expression level of CCR8, interleukin 2 receptor alpha-chain (IL2RA), and Foxp3 indicate regulatory T cell (Treg) infiltration and contribute to the immunosuppression of T cells against cancer." (PMID 34820403, 2021). "Usually, the higher the number of infiltrated FOXP3 + Tregs in cancer, the poorer the prognosis because Tregs maintain immune homeostasis and inhibit immune responses in various diseases, including cancer." (PMID 34414959, 2021). "In hot tumors, the CD4 T cells and FoxP3 cells were found in 4 out of 10 tumors in the stroma and in between the cancer cells; in 6 out of 10 cases, only within the stroma." (PMID 34778030, 2021). "While Foxp3 is typically utilised to identify Tregs, here the investigators demonstrated the presence of Foxp3 positive cancer cells." (PMID 33100327, 2021). "Our results showing that the high Foxp3+ T cell subgroup showed a significantly poorer prognosis than the low Foxp3+ T cell subgroup support the findings of previous reports on various cancers, including PDAC." (PMID 34758773, 2021). "Regulatory T cells (Tregs) expressing forkhead box protein P3 (FOXP3) are a critical component of immune systems with pivotal roles not only in the maintenance of self-tolerance but also in the suppression of anti-cancer immunity." (PMID 33665689, 2021).
cancer (continued). "Correlation analysis between miR-155 gene expression and SOCS1, TAB2, and Foxp3 in cachectic pancreatic or NSCL cancer patients (Spearman’s correlation)." (PMID 34900737, 2021). "The CD8+/CD4+Foxp3+ ratio is known to be a marker that correlates with prolonged cancer patient survival." (PMID 34439192, 2021). "High FOXP3 or density of NK cells also have been reported to correlate with the prognosis of recurrence in cancer." (PMID 34484217, 2021). "Other stromal components, such as cancer associated fibroblasts (CAF), contribute to lactate production that preferentially selects for intratumoral CD4+ Foxp3+ populations through a NF-kB-FoxP3 axis." (PMID 33868263, 2021). "Tregs are CD3+ CD4+ CD25+ FOXP3+ CD127low T cells that are recruited by cancer cells via surface ligands like CCL22 and CCL35." (PMID 33530455, 2021). "As recent review reported several pathways in Treg from cancers including Foxp3, IRF4, PI3/AKT/FoxO axis, Helios, Eos, Nr4a, Bach2, E proteins and their inhibitor of DNA-binding (Id) counterparts, STAT3, and NF-kB." (PMID 34084175, 2021). "FOXP3 is a complex transcription factor that includes several domains performing different and sometimes opposing functions affecting cancer growth." (PMID 33671179, 2021). "The correlation between the presence of FOXP3+ Tregs and patients’ survival has been extensively studied in many cancer types, which remains conflicting." (PMID 34006632, 2021). "The authors found that CRP levels were significantly higher in patients with strong infiltration of CD8+ Foxp3+ cells, and cancer-specific survival was significantly worse in these patients than in patients with weak infiltration." (PMID 33635904, 2021). "Tregs suppress the inflammatory response and control anti-cancer immunity and are identified by the expression of the master transcription factor forkhead box protein p3 (FOXP3)." (PMID 33659922, 2021). "Another interesting Treg subset in the setting of intestinal inflammation-induced cancer is the Foxp3+RORγt+ T cell." (PMID 34884543, 2021). "The ratio between CD8+ and CD4+ cells to FoxP3+CD8+ Tregs is a key prognostic factor for different types of cancer." (PMID 34707136, 2021). "Several studies reported that 18F-FDG PET/CT highly reflects the immune status defined by CD8 + and Foxp3 + TIL counts in several types of cancers." (PMID 33712681, 2021). "With our current results of FOXP3-mediated ATF3 regulation, future studies are indeed necessary to explore the FOXP3 spliced isoforms in ATF3 regulation as well as the role of SRSF1 in FOXP3 isoform regulation, especially in the cancer field." (PMID 34768829, 2021). "Immunological regulatory protein such as tumour necrosis factor (TNF), interferon-γ (IFN-γ) and forkhead box P3 (FOXP3) have shown direct/ indirect effects on cancer cell." (PMID 33509300, 2021). "In this study, B cells were more highly expressed in patient D but poorly expressed in both patient A and patient B. Besides, the presence of high numbers of FOXP3+ T cells in cancer tissues predicts worse relapse-free survival and decreased overall survival." (PMID 34239944, 2021). "Forkhead box protein P3 (FOXP3) expression is observed in cancer cells and infiltrated regulatory T cells (Tregs)." (PMID 34414959, 2021). "While aberrant FOXP3 expression has been associated with several types of cancer, little is known regarding the risk of cancer in patients with IPEX harboring the characteristic FOXP3 mutation." (PMID 34258086, 2021). "In an orthotopic cancer model, transient FOXP3-expressing Treg depletion in combination with systemic administration of anti-PD-1 Ab successfully induced severe hepatic irAEs32." (PMID 33927311, 2021). "In the context of IBD-associated cancer, studies in the AOM/DSS mouse model have shown that ablation of CD4+Foxp3+ Treg cells suppressed tumor growth, which was associated with increased numbers of CD8+IFN-γ+ Granzyme B-producing effector T cells." (PMID 34884543, 2021).
cancer (continued). "Memory T-cells, anergic T-cells, exhausted T-cells, and even a consistent amount of immunosuppressive Foxp3+ and Foxp3− T-cells are present in the reservoir of total TILs in different cancer types, thus limiting the frequency of antitumor effector cells." (PMID 33530328, 2021). "Regulatory T cells (Tregs) are an immunosuppressive subset of forkhead box P3 (Foxp-3+) CD4+ CD25high T cells known to be determinant in the regulation of the immune response to cancer." (PMID 33602280, 2021). "In general, lower numbers of CD3+ lymphocytes are usually associated with poorer prognosis due to a suppressed immune response, and FOXP3 is known to suppress antitumor responses and facilitate cancer progression." (PMID 34076969, 2021). "We found that intratumoural lymphocytes expressing CD8, PD-1, FOXP3, TIM3, and LAG3, as well as PD-L1-expressing carcinoma cells, were each associated with better survival, independent from standard clinicopathologic factors." (PMID 33804486, 2021). "When analyzed for regulatory T cells, the cases with concurrent low CSF-1R+ carcinoma cells and low FOXP3 iTILs exhibit the best outcome (HR 0.71, 95% CI 0.60–0.86; p = 0.001)." (PMID 34830923, 2021). "In fact, the density of CD4+ and CD4+Foxp3+ T-cells in the radiation group was statistically higher than the untreated group in both areas of the carcinoma and the stroma." (PMID 34647108, 2021). "The density of CD4+ T-cells, CD8+ T-cells, and CD4+ Foxp3-positive (Foxp3+) T-cells were statistically higher in both carcinoma and stromal areas in the primary specimens when compared with matched brain metastases (p < 0.0001, respectively)." (PMID 34647108, 2021). "In this study, we have illustrated that the densities of CD4+ T-cells and CD8+ T-cells in carcinoma and stromal areas, and CD4+Foxp3+ T-cells in the carcinoma area of the brain metastases were positively correlated with OS." (PMID 34647108, 2021). "The densities of CD4+ and CD4+Foxp3+ T-cells in the radiation group were statistically higher than the untreated group in carcinoma and stromal areas (p = 0.0343, p = 0.0173)." (PMID 34647108, 2021). "Treg cells, especially the FOXP3+ ones, suppress immune responses and maintain cancer immune tolerance, the frequency of which has been applied as an independent risk factor of cancer relapse." (PMID 33145341, 2020). "Presence of normal-ASCs and cancer-ASCs in theculture increased Helios+ T cells in the population ofCD4+CD25+FOXP3+ cells." (PMID 31721539, 2020). "The resultsshowed that co-culturing naïve CD4+ T cells with cancer-ASCs and normal-ASCs caused decreased population ofCD4+CD25+FOXP3-Helios+ in comparison with the controlgroup (P=0.028 and 0.028, respectively)." (PMID 31721539, 2020). "This stochastic activity of the Foxp3 promoter—and “leaky” expression of the Foxp3cre allele—may lead to recombination of the loxP-flanked regions in other immune cells that are involved in cancer immunity, such as CD4+ Tconv, CD8+ T cells, and also myeloid cell subsets." (PMID 33143070, 2020). "High IDO1 expression has been shown to correlate with reduced levels of infiltrating CD3+ T cells, CD8+ T cells, CD57+ NK cells, B cells and increased levels of forkhead box P3 (Foxp3)+ Tregs48–52 in different cancer types." (PMID 31819194, 2020). "In recent years, alternative strategies have aimed at targeting Foxp3 cofactors or other pathways, transcription factors, and epigenetic regulators involved in Treg cell biology in cancer; these will be the focus of this review." (PMID 33143070, 2020). "CD47 is likely involved in the process of evading immunological eradication, and FOXP3 is mainly considered as a biomarker of Treg cells that impede the antitumor immune responses in cancer patients." (PMID 32118031, 2020).
cancer (continued). "Our group has described TCRms specific for a cancer germline antigen, PRAME, which is widely expressed in various cancers (recognizing ALYVDSLFFL/HLA-A*02:01), and FOXP3, the hallmark protein for Tregs (recognizing TLIRWAILEA/HLA-A*02:01)." (PMID 33569049, 2020). "We recently reported that cancer Forkhead box protein 3 (Cancer-FOXP3 or C-FOXP3) promoted immune evasion of PDAC by recruiting Treg cells into PDAC via upregulation of CCL5." (PMID 32300119, 2020). "The class I HDAC inhibitor Entinostat, currently under investigation in different types of cancer, was shown to decrease Foxp3 expression in vitro and in vivo." (PMID 33143070, 2020). "According to the report, not only CD8 + lymphocytes that suppress cancer progression but also FOXP3-positive lymphocytes that promote cancer progression are reduced." (PMID 32590956, 2020). "Mean ± SEM percentageof T cells with CD4+CD25+FOXP3+Helios+ phenotypewere 15.59 ± 4.6%, 12.63 ± 3.6%, and 5.90 ± 2.6% inthe presence of cancer-ASCs and normal-ASCs and inthe control group, respectively." (PMID 31721539, 2020). "We further performed double staining for CA9 and FOXP3 on 20 selected cases that expressed CA9 in 30–60% of the cancer cell population, containing areas with positive expression and lack of expression." (PMID 32066909, 2020). "More importantly, CCR5 is preferentially expressed on CD4+Foxp3+ Tregs over CD4+Foxp3− T-cells in healthy individuals and more so in cancer patients." (PMID 33375291, 2020). "Our present findings suggest that targeting factors such as USP44 and USP7 that promote FOXP3 expression at the protein level is a strategy that offers exciting possibilities for the fine‐tuning of immune responses in cancer." (PMID 32644293, 2020). "CD4+ regulatory T cells (Tregs) expressing transcription factor FOXP3 are highly immunosuppressive, and in malignant tumors, they promote cancer progression by suppressing antitumor immunity." (PMID 33614479, 2020). "CD4+ T-cells had a FOXP3+ regulatory phenotype, occasionally as the minor population, as shown in other cancer models." (PMID 31959856, 2020). "Among immune cells, Foxp3+ regulatory T cells (Treg cells) are potent inhibitors of cancer immunity, and their presence within solid tumors is generally associated with a poor prognosis." (PMID 33143070, 2020). "The increased number of infiltrating FOXP3+ Tregs was shown to be highly correlated with the patient outcome in several cancers." (PMID 33062072, 2020). "In the present study, results indicated that FOXP3+ Treg-mediated immune tolerance promotes cancer cell proliferation and metastasis." (PMID 33062072, 2020). "Because of its critical function in shaping the Treg cell transcriptome and function, Foxp3 itself is an attractive target for cancer immunotherapy." (PMID 33143070, 2020). "Tregs recruitment by cancer-Foxp3 was impaired by the neutralization of CCL5, inhibiting the growth of PDAC." (PMID 32680511, 2020). "In the analysis carried out with the double positivity scoring method, the densities of CD3+Foxp3+ and CD8+Foxp3+ cells were significantly lower in CAC patients than in sporadic cancer patients (all, p < 0.001)." (PMID 31048714, 2019). "At the molecular level, Nurr1 has been reported to regulate regulatory T cell development through activation of the Foxp3 signaling pathway, and Nurr1-modified T cells have therapeutic potential for treating cancer." (PMID 33817160, 2019). "CD4+/CD25+/FOXP3+ Treg contributes to immunosuppression and cancer progression by reducing the anticancer immunity of CD4+ or CD8+ effector T cells." (PMID 31815635, 2019). "Tregs, including induced Tregs and naturally arising Foxp3+ nTregs, together play vital roles in immune escape and immunotherapy failure in cancer patients." (PMID 31823770, 2019).